COG2 (component of oligomeric golgi complex 2)
Description:
Required for normal Golgi morphology and function.
Synonyms: LDLC; CDG2Q
Tractability: Antibody: UniProt places it where antibodies can reach, with high confidence. PROTAC: ubiquitination databases record sites on it; its protein half-life has been measured.
Target class: Other cytosolic protein
Gene: Protein-coding gene on chromosome 1 (230,642,464 to 230,693,985, forward strand). Ensembl gene ENSG00000135775.
Subcellular location: Golgi apparatus membrane
Subcellular location (Human Protein Atlas): Golgi apparatus
Pathways (Reactome):
Vesicle-mediated transport: COPI-mediated anterograde transport; Intra-Golgi traffic; Retrograde transport at the Trans-Golgi-Network
Gene Ontology:
Molecular function: protein binding; protein-containing complex binding
Biological process: Golgi organization; intra-Golgi vesicle-mediated transport; retrograde transport, vesicle recycling within Golgi; protein transport
Cellular component: Golgi stack; Golgi transport complex; Golgi membrane; trans-Golgi network membrane; membrane
Genetic constraint (gnomAD): Loss-of-function variants: 38 observed, 68.79 expected, observed/expected ratio (o/e) 0.55, 90% interval 0.43 to 0.72. The upper end of that interval is the gene's LOEUF score, 0.72, which puts it in group 2 of 6, group 1 being the genes least tolerant of losing a copy. Missense variants: 662 observed, 737.28 expected, observed/expected ratio (o/e) 0.9, 90% interval 0.84 to 0.96. Synonymous variants: 274 observed, 277.15 expected, observed/expected ratio (o/e) 0.99, 90% interval 0.89 to 1.09.
Gene-disease validity (ClinGen):
ClinGen rates the evidence that COG2 causes each of these diseases.
congenital disorder of glycosylation, type IIq (autosomal recessive): Limited.
Homologues: Orthologues: chimpanzee COG2 (99% identical), macaque COG2 (98% identical), dog COG2 (92% identical), rabbit COG2 (91% identical), pig COG2 (90% identical), guinea pig COG2 (87% identical), mouse Cog2 (85% identical), rat Cog2 (85% identical), tropical clawed frog cog2 (70% identical), zebrafish cog2 (69% identical), Drosophila melanogaster Cog2 (33% identical), Caenorhabditis elegans cogc-2 (23% identical).
Diseases named in the same sentence as COG2 in open-access papers:
COG2 is named in the same sentence as 66 diseases in open-access papers, as found by Europe PMC text mining. Sharing a sentence is not in itself a finding about the gene and the disease. The quoted sentences say what the papers report.
tumor (7 papers, 2021 to 2025). "The highest mRNA expression of COG2 was found in tumour grade 2, and the mRNA expression of COG3 was only associated with grade 3." (PMID 34539936, 2021). "Similarly, high mRNA expression of 5 of all COG isoforms (COG2, COG3, COG5, COG6, COG7, and COG8) was also correlated with favourable OS of KIRC patients with tumour grade 2, grade 3, and grade 4, while patients with low mRNA expression of COG4 showed higher survival rate." (PMID 34539936, 2021).
COG2 also shares sentences with these, for which no sentence is quoted: atherosclerosis (24 papers); coronary heart disease (11); dyslipidemia (10); diabetes (8); Hypertension (7); familial hypercholesterolemia (6); cardiovascular disease (5); hyperlipidemia (5); ischemic stroke (5); cancer (4); breast carcinoma (3); COVID-19 (3); Hypercholesterolemia (3); Sepsis (3); acute coronary syndrome (2); atrial fibrillation (2); cerebral small vessel disease (2); fatty liver (2); heart failure (2); hepatocellular carcinoma (2); myocardial infarction (2); Stroke (2); allergic asthma (1); Alzheimer disease (1); aortic valve stenosis (1); arteriosclerosis (1); Atrophy (1); brain tumor (1); cataract (1); Cerebellar atrophy (1).
A further 35 diseases each share a sentence with COG2 in 1 paper.